DGAT1 (diacylglycerol O-acyltransferase 1)
Diseases named in the same sentence as DGAT1 in open-access papers (continued):
Sharing a sentence is not in itself a finding about the gene and the disease.
bile reflux (1 paper, 2023). "Compared with the control group, the expressions of Fabp1 and Dgat1 in gastric antrum tissue of GIM rats induced by bile reflux were increased." (PMID 37206332, 2023).
colorectal adenocarcinoma (1 paper, 2025). The most common type of colorectal carcinoma. "Among various solid tumors, DGAT1 has the highest expression level in colorectal adenocarcinoma." (PMID 39856069, 2025).
COVID-19 (1 paper, 2021). A disease caused by infection with severe acute respiratory syndrome coronavirus 2. "Importantly, we showed that that Xanthohumol, a DGAT1/2 inhibitor with both antiviral and anti-inflammatory properties, may serve as an orally available treatment option for COVID-19." (PMID 34702802, 2021).
endometrial cancer (1 paper, 2025). Primary or metastatic malignant neoplasm involving the endometrium (mucous membrane that lines the endometrial cavity). "DGAT1 inhibitors significantly suppressed cleaved caspase-3 (the key executioner of apoptosis) in endometrial cancer, indicating an important role for DGAT1 in regulating cell apoptosis." (PMID 40554491, 2025).
endometrial tumor (1 paper, 2025). "Our laboratory analyses further confirmed the upregulation of both DGAT1 and DGAT2 in endometrial tumor tissues (unpublished data), supporting their role in lipid accumulation and reinforcing their inclusion in the diagnostic model." (PMID 40804485, 2025).
inflammatory skin disease (1 paper, 2026). Inflammatory skin disorders covers a broad category that includes many conditions ranging in severity, from mild itching to grave medical health complications These disorders are common in people of all ages and races. "By linking DGAT1 activity with RA signaling, this work uncovers a previously unrecognized pathway contributing to epidermal physiology and inflammatory skin disease." (PMID 42268475, 2026).
ischemic stroke (1 paper, 2025). A stroke disorder caused by obstruction of blood flow to the brain, due to thrombotic (local blood clot formation) or embolic (due to a blood clot or other material traveling from another site) event. "This study investigated DGAT1 in ischemic stroke using middle cerebral artery occlusion (MCAO) rat models and highly differentiated PC12 cells subjected to oxygen–glucose deprivation/reoxygenation (OGD/R)." (PMID 40375180, 2025). "Recent studies have increasingly shown that abnormal lipid metabolism is a crucial pathological mechanism in the progression of ischemic stroke, and DGAT1 is a promising candidate as a key regulatory molecule in this process." (PMID 40375180, 2025). "Overall, this study provides preliminary insights into DGAT1 as a potential therapeutic target for ischemic stroke." (PMID 40375180, 2025). "This study represents the first investigation into the potential role of DGAT1 in ischemic stroke." (PMID 40375180, 2025). "In summary, our study suggests that DGAT1 inhibition may provide neuroprotection in ischemic stroke by upregulating β-oxidation, improving mitochondrial function, and suppressing ferroptosis." (PMID 40375180, 2025). "Despite the potential of targeting metabolic pathways as a therapeutic strategy for ischemic stroke, the specific role of DGAT1 in this context remains unclear." (PMID 40375180, 2025). "Our study suggests that DGAT1 inhibition may enhance β-oxidation and mitochondrial function, thereby increasing Gpx4 levels, suppressing ferroptosis, and ultimately exerting neuroprotective effects in ischemic stroke." (PMID 40375180, 2025). "Diacylglycerol O-acyltransferase 1 (DGAT1) is crucial for triglyceride synthesis, yet its role in ischemic stroke remains unclear." (PMID 40375180, 2025).
lipid metabolism disorder (1 paper, 2022). "Analysis of underlying mechanisms showed that DEHP may cause lipid metabolism disorder through hepatic PPAR, the main protein of metabolic homeostasis regulation, and upregulate DGAT1, the key enzyme responsible for synthesis and storage of TGs in the liver." (PMID 36483930, 2022).
multiple sclerosis (1 paper, 2024). A progressive autoimmune disorder affecting the central nervous system resulting in demyelination. "For example, the DGAT1-mediated synthesis of retinol esters and the prevention of RA formation has been shown to regulate T cell differentiation in a mouse model of multiple sclerosis." (PMID 39043892, 2024).
overnutrition (1 paper, 2024). An imbalanced nutritional status resulting from excessive intake of nutrients. "Because both DGAT1 and DGAT2 act on liver lipid droplet formation due to overnutrition, inhibition of DGAT1 alone does not usually improve lipid droplets." (PMID 38807157, 2024).
salmonellosis (1 paper, 2024). Infections with bacteria of the genus salmonella. "Salmonellosis induces a time-dependent increase in LD formation in macrophages, and the inhibition of diacylglycerol O-acyltransferase 1 and cytosolic phospholipase A2 significantly reduces intracellular bacterial proliferation." (PMID 38690912, 2024).
Sepsis (1 paper, 2025). Sepsis is defined as life-threatening organ dysfunction caused by a dysregulated host response to infection. "Expression of lipogenic enzyme DGAT1 (Dgat1) was not altered, but lipolytic enzymes ATGL (Pnlpa2) and HSL (Lipe) displayed elevated expression both in acute and prolonged sepsis." (PMID 39821755, 2025).
severe combined immunodeficiency (1 paper, 2019). Severe combined immunodeficiency (SCID) comprises a group of rare monogenic primary immunodeficiency disorders characterized by a lack of functional peripheral T lymphocytes resulting in early-onset severe respiratory infections and failure to thrive. "To assess whether the treatment with a DGAT1 inhibitor was able to suppress cancer progression in vivo, we implanted grafts containing PC-3 cells with or without DGAT1 inhibitor under the kidney capsule of SCID mice (mice with severe combined immunodeficiency)." (PMID 30816200, 2019).
Stillbirth (1 paper, 2014). Death of the fetus in utero after at least 22 weeks of gestation. "However, the influence of this QTL on SDGBV for direct genetic effect for stillbirth was less than the effect of DGAT1 on the SDGBV for fat yield." (PMID 24990472, 2014). "Differences in allele frequencies of the DGAT1 gene and of the QTL for the direct genetic effect for stillbirth might explain these findings." (PMID 24990472, 2014).
Stroke (1 paper, 2025). Sudden impairment of blood flow to a part of the brain due to occlusion or rupture of an artery to the brain. "Finally, the long-term effects of DGAT1 inhibition on neuroplasticity and post-stroke functional recovery remain important topics for future investigation." (PMID 40375180, 2025).
tuberculosis (1 paper, 2022). A chronic, recurrent infection caused by the bacterium Mycobacterium tuberculosis. "Looking to the future of TB drug discovery, known inhibitors of DGAT1 should be screened against M. tuberculosis to establish whether any existing drugs could be exploited as anti-mycobacterial agents." (PMID 36277080, 2022).
uveitis (1 paper, 2025). An inflammatory process affecting a part of or the entire uvea. "Collectively, our study focused on elucidating the regulatory mechanisms underlying Th17 cell survival and proposed that targeting DGAT1 may hold promise as a therapeutic approach for uveitis." (PMID 40197365, 2025). "Moreover, we validated the upregulation of DGAT1 in CD4+ T cells from patients with Vogt-Koyanagi-Harada (VKH) disease, a human uveitis." (PMID 40197365, 2025).
Wilson disease (1 paper, 2020). A very rare inherited multisystemic disease presenting non-specific neurological, hepatic, psychiatric or osseo-muscular manifestations due to excessive copper deposition in the body. "Moreover, prime editing functionally recovers disease-causing mutations in intestinal organoids from patients with DGAT1-deficiency and liver organoids from a patient with Wilson disease (ATP7B)." (PMID 33097693, 2020).
cancer (52 papers, 2012 to 2026). A tumor composed of atypical neoplastic, often pleomorphic cells that invade other tissues. "U. dioica significantly suppressed the expression of Brca1, Brca2, Fas, Lpl, Dgat1 and Mcp1 genes, resulting in significant changes in lipid metabolism, cancer susceptibility and inflammation." (PMID 40153121, 2025). "A controversial association between the prognosis of cancer patients and the expression levels of DGAT1 and DGAT2 in different types of tumors has been reported." (PMID 38500157, 2024). "Strikingly, DGAT1 amplification was associated with significantly poorer progression-free survival across multiple cancer types." (PMID 35732120, 2022). "DGAT-1 inhibition causes cancer cell death by inducing mitochondrial damage and elevated ROS formation, supporting the use of MMV024937 as a promising anti-tumor drug." (PMID 34299074, 2021). "We demonstrate that KU60019-mediated remodeling coordinates miR-1273g-3p upregulation and subsequent DGAT1 suppression, ultimately impairing cancer cell migration and inducing apoptosis." (PMID 40554491, 2025). "IC2-stimulated LD formation was mostly caused by the disruptions of mitochondrial functions and relied on the functions of ACC and DGAT1 in cancer cells." (PMID 39725994, 2024). "The co-occurrence of DGAT1 amplification with FASN, CD36, or MAGL amplification in human cancers was significant, arguing for these co-aberrations being synergistic, in keeping with DGAT1 facilitating safe accumulation of FA in cancer cells." (PMID 35732120, 2022). "Abundant LD have been observed in a range of cancers, consistent with widespread up-regulation of DGAT1, indicating that DGAT1 is likely to perform an oncogenic role in these other cancers too." (PMID 35732120, 2022). "A growing number of evidences showed that elevated expression of DGAT1 in cancer tissue indicated a poor outcome in cancer patients." (PMID 33750350, 2021). "Currently, DGAT1/2 is known to play a positive regulatory role in many cancers related to lipid accumulation." (PMID 34604067, 2021). "Next, we analyzed DGAT1 level in cancer tissues upon tumor grades or individual cancer stages, and the results showed that during the deterioration of diseases, DGAT1 decreased in transcript level." (PMID 33750350, 2021). "DGAT1 was significantly overexpressed in stage IV cancer tissues compared to the stage III specimens." (PMID 34095320, 2021). "Diacylglycerol-acyltransferase 1 (DGAT1) plays an important role in the energy storage and is involved in cancer progression." (PMID 33750350, 2021). "We initially investigated expression of DGAT1 in pan-cancer of patients by collecting data from the Oncomine database." (PMID 33750350, 2021). "We also documented a significant upregulation of DGAT1 mRNA and protein expression in pH 6.5-adapted cancer cells that was completely prevented upon TGF-β2 silencing or TGF-βRI blockade; DGAT2 expression was not altered in response to Trabedersen or SB431542." (PMID 31974393, 2020). "Gpam, Agpat2, and Dgat1 are critical enzymes involved in TG biosynthesis and Gpam overexpression correlates with cancer cell migration." (PMID 32156004, 2020). "DGAT activation in order to enhance storage would be a potential strategy for cancer prevention, since DGAT-1 overexpression reduces proliferation and invasiveness in human fibroblasts." (PMID 33050166, 2020). "Depletion of the ncMTOC protein GM130 reduced tumor cell proliferation and migration supporting a new mechanism for anti-DGAT1 bioactivities in cancer." (PMID 30816200, 2019). "DGAT2 protein levels were significantly higher than DGAT1 in the same cancer cell lines." (PMID 41041279, 2025). "Contrary to other studies in which the depletion of LDs due to the inhibition of DGAT1 confers sensitization to apoptosis or ferroptosis in cancer models, in this study, the inhibition of DGAT1 blocks ferroptosis induced by IKE + DHAA selectively in IKE-resistant cancer models." (PMID 37752118, 2023).
cancer (continued). "DGAT1 in cancer tissue indicated a poor outcome in GC patients." (PMID 35785165, 2022). "Thus, future studies should focus on evaluating the efficacy of DGAT1 inhibition alone, or in combination with inhibition of anti-ROS mechanisms, to induce the most well-tolerated and beneficial outcomes for cancer patients." (PMID 35732120, 2022). "Evidently, cancer cells, having elevated FA, require more DGAT1 to achieve this." (PMID 35732120, 2022). "Furthermore, many publications have shown that DGAT1 is a better target than DGAT2 for cancer therapy." (PMID 36009491, 2022). "Furthermore, DGAT1 was highly expressed in histological grade 3/4 cancer tissues compared to that in histological grade 1/2." (PMID 34095320, 2021). "Results showed that DGAT1 level was increased in the cancer tissues." (PMID 33750350, 2021). "For instance, we observe significant negative correlation between the EMT score and the esterification gene (DGAT1) in 4 cancer types (BRCA, COADREAD, KIRC, LUAD), and significant positive correlation with lipase (LIPE) in 3 cancer types (BRCA, COADREAD, PRAD)." (PMID 26725848, 2016). "Thus, pharmacological inhibition of DGAT1/2 may have therapeutic potential in the treatment of cancer, including EC." (PMID 38786008, 2024). "Thus, from a cancer genomics perspective, DGAT1 exhibits the hallmarks of an oncogene." (PMID 35732120, 2022). "Therefore, we verified the effect of DGAT1 in BC cells, and the results confirmed the promoting effects of DGAT1 in BC cell proliferation and migration, which were consistent with the results in other cancer types." (PMID 34976839, 2021). "Existing research consistently highlights the overexpression of DGAT1 and DGAT2 in various cancers, including prostate, breast, and OCs." (PMID 41041279, 2025). "Correlation analyses revealed a positive correlation between DGAT1 and DGAT2 mRNA levels in cancer cell lines (Spearman r = 0.813, p < 0.017), suggesting potential coordinated regulation between these isoforms at the transcriptional level." (PMID 41041279, 2025). "DGAT1 and DGAT2 are promising targets in cancer treatment, playing critical roles in LD formation and tumor progression, highlighting their potential for developing new therapeutic strategies." (PMID 41041279, 2025). "The results showed that the DGAT1 inhibitor increased both PARP and caspase-3 cleavage in IC2-treated cancer cells, thereby confirming the enhanced apoptotic response." (PMID 39725994, 2024). "The results of this study demonstrate that LD formation occurs in a DGAT1- and autophagy-dependent manner during amino acid starvation in HeLa- and MDA-MB-231 cancer cells." (PMID 37835551, 2023). "Our findings have shown that expression of GPAT4 and DGAT1 were reduced in NAT10‐depleted cancer cells and palmitate‐loaded NAT10‐depleted cancer cells suggesting that NAT10 depletion implicates in reduced lipid droplet formation." (PMID 36149760, 2022). "It is still unclear why DGAT1 and DGAT2 behave differently in various cell types and which transcription factor regulates their expression in cancer cells." (PMID 36009491, 2022). "Altogether these data indicate that chronic acidosis induces LD formation in cancer cells, with CD36 and DGAT1 as key players to mediate LD biogenesis through the uptake of exogenous FA and triglyceride synthesis, respectively." (PMID 31974393, 2020). "On the contrary, inhibition of DGAT1 and DGAT2 disrupts TG fatty acid composition and compromises in vivo cancer growth by increasing apoptosis and reducing proliferation of cancer cells." (PMID 31315616, 2019). "Among other genes that were clustered with STS were several genes with ubiquitous expression in the normal tissues and documented overexpression in cancers: SLC26A6, TOMM40L, AKR1B1, NDRG2 and DGAT1 (based on TCGA data)." (PMID 29088719, 2017).
cancer (continued). "Blocking of DGAT1 leads to blockage of storage while blockage of ABHD5 leads to blockage of usage; hence both the siRNA treatments lead to unavailability of FA for cancer cell proliferation and decreased growth." (PMID 28877685, 2017). "Consistently, inhibition of DGAT1 in OSCC cells within our study also blocked the formation of LDs and attenuated their migration and invasion, which further verified the essential role of LDs biogenesis in cancer progression." (PMID 39875372, 2025). "Inhibition of TAG synthesis by targeting DGAT1 and DGAT2 with specific small inhibitors effectively depleted the formation of LDs and had differential effects on cell growth depending on the type of FA in cancer cells." (PMID 38786008, 2024). "Furthermore, we evaluated the expression of Diacylglycerol Acyltransferases (DGAT) 1 and 2 which participate in TAG synthesis, and found an increase in DGAT1 and DGAT2 expression in Elovl5-silenced cancer cells." (PMID 36056008, 2022). "Furthermore, other CRRGs, such as PPA2, DGAT1, and CABYR, have been shown to be involved in the oncogenic effects of other cancers and to affect patient prognosis, despite the fact that related studies are uncommon in BC." (PMID 36685904, 2022). "Likewise, DGAT1 and DGAT2 are frequently overexpressed in many cancers while being unchanged in the murine liver tumors." (PMID 34629057, 2021). "Unexpectedly, survival curve analysis based on first progression analysis showed that elevated DGAT1 expression in cancer tissues has no impact on the survival time of the indicated patients." (PMID 33750350, 2021). "Expressions of both CD36 and DGAT1, the main entry path for FA in the cytosol and the final actor of their accumulation as neutral lipids, respectively, are regulated by TGF-β2 produced by acidosis-adapted cancer cells." (PMID 31974393, 2020). "We found that upon LD deprivation, either by forskolin or DGAT1 inhibitor treatment (before the assay), 6.5/SiHa cancer cells exhibited a reduced invasiveness in modified Boyden chambers; similar results were obtained using HCT-116 cancer cells." (PMID 31974393, 2020). "Since both DGAT1 and ABHD5 are overexpressed in cancer cells and CTCs vigorously uptake lipid as compared to PBMCs, targeting them may represent a new oncolytic approach." (PMID 28877685, 2017). "Since DGAT1 and DGAT2 are enzymes that catalyze the last step in TAG synthesis and control the biogenesis of LDs, inhibition of their functions results in an increased concentration of free FAs and other lipid species in the cytoplasm, ultimately leading to higher “lipotoxicity” for cancer cells." (PMID 38786008, 2024). "DGAT2 deserves as much attention as DGAT1, if not more, in cancer research." (PMID 36439875, 2022). "Could other proteins in addition to DGAT1 and SOAT1 serve as druggable targets for cancer therapy?" (PMID 36009491, 2022). "To support this hypothesis, we treated 6.5/cancer cells with GW6471, an antagonist of PPARα (a major FA-activated transcription factor regulating FA metabolism) and showed that the expression of DGAT1 but also that of mitochondrial fatty acyl-CoA transporter CPT1 were decreased." (PMID 31974393, 2020). "However, DGAT1 expression in the tumors appeared to be higher than ATGL, thereby, leading to a net gain (lipogenesis > lipolysis) in intracellular lipid content consistently observed in the cancer cells." (PMID 30816200, 2019). "The potential anti-tumor activity of DGAT1 inhibitors in cancer has not been explored." (PMID 30816200, 2019). "Interestingly, the treatment with PEDF reduced the baseline levels of DGAT1 protein (PC-3 PEDF vs PC-3 CTR: 69.5 ± 0.7 vs 123.5 ± 1.5; P < 0.001), thus, allowing a negative feedback loop to suppress endogenous DGAT1 protein in cancer cells." (PMID 30816200, 2019).